SLC9C1 (solute carrier family 9 member C1)
Description:
Sperm-specific solute carrier involved in intracellular pH regulation of spermatozoa. Required for sperm motility and fertility. Involved in sperm cell hyperactivation, a step needed for sperm motility which is essential late in the preparation of sperm for fertilization. Required for the expression and bicarbonate regulation of the soluble adenylyl cyclase (sAC) (By similarity).
Synonyms: NHE-10; SLC9A10; NHE; sperm-NHE
Tractability: Antibody: UniProt predicts a signal peptide or a membrane-spanning region; its Gene Ontology location is reachable by antibodies, with medium confidence.
Gene: Protein-coding gene on chromosome 3 (112,140,898 to 112,294,227, reverse strand). Ensembl gene ENSG00000172139.
Subcellular location: Cell projection, cilium, flagellum membrane
Pathways (Reactome):
Transport of small molecules: Stimuli-sensing channels
Gene Ontology:
Molecular function: antiporter activity; monoatomic ion channel activity; sodium:proton antiporter activity
Biological process: regulation of intracellular pH; sodium ion import across plasma membrane; monoatomic cation transport; monoatomic ion transport; proton transmembrane transport; transmembrane transport
Cellular component: membrane; motile cilium
Genetic constraint (gnomAD): Loss-of-function variants: 68 observed, 101 expected, observed/expected ratio (o/e) 0.67, 90% interval 0.55 to 0.82. The upper end of that interval is the gene's LOEUF score, 0.82, which puts it in group 3 of 6, group 1 being the genes least tolerant of losing a copy. Missense variants: 1,153 observed, 1,185.7 expected, observed/expected ratio (o/e) 0.97, 90% interval 0.93 to 1.02. Synonymous variants: 370 observed, 384.49 expected, observed/expected ratio (o/e) 0.96, 90% interval 0.88 to 1.05.
Homologues: Orthologues: chimpanzee SLC9C1 (98% identical), macaque SLC9C1 (84% identical), rabbit SLC9C1 (71% identical), dog SLC9C1 (70% identical), pig SLC9C1 (69% identical), rat Slc9c1 (67% identical), mouse Slc9c1 (66% identical), guinea pig SLC9C1 (59% identical), Drosophila melanogaster Nhe2 (11% identical), Caenorhabditis elegans nhx-5 (8% identical), Drosophila melanogaster Nhe3 (8% identical), Caenorhabditis elegans nhx-2 (8% identical), and 2 more. Paralogues in human: SLC9C2 (27% identical), SLC9A1 (11% identical), SLC9A3 (11% identical), SLC9A5 (10% identical), SLC9A2 (10% identical), SLC9A7 (9% identical), SLC9A4 (9% identical), SLC9A9 (9% identical), SLC9A6 (9% identical), SLC9A8 (7% identical).
Diseases named in the same sentence as SLC9C1 in open-access papers:
SLC9C1 is named in the same sentence as 14 diseases in open-access papers, as found by Europe PMC text mining. Sharing a sentence is not in itself a finding about the gene and the disease. The quoted sentences say what the papers report.
Infertility (10 papers, 2012 to 2025). "Genetic deletion of sNHE causes infertility in mice, and mutations in SLC9C1 (sNHE) cause severe defects in human sperm motility and fertility, indicating the importance of this molecule in sperm function." (PMID 39416520, 2024). "Even more recent analysis of an infertile male presenting with asthenozoospermia found that this patient bares a homozygous mutation in SLC9C1." (PMID 37834431, 2023). "Very recently, the importance of SLC9C1 in human functional asthenozoospermia was confirmed by the finding of a homozygous truncating mutation in an infertile patient." (PMID 35409285, 2022). "SLC9C1 (sNHE) disruption in the mouse model caused infertility due to asthenozoospermia and capacitation defects, both phenotypes being partially rescued by sperm alkalinization and largely rescued by supplementation with cAMP analogs." (PMID 35409285, 2022). "Interestingly, the infertility phenotype of the double-KO is similar to that observed in NHE10/sNHE-KO mice (SLC9C1)." (PMID 38786087, 2024).
male infertility (3 papers, 2023 to 2025). The inability of the male to effect fertilization of an ovum after a specified period of unprotected intercourse. "Knockout (KO) studies have shown that SLC9C1 deficiency causes immotile spermatozoa and male infertility in mice, which can be rescued by cell-permeable cAMP analogs or photoactivated adenylyl cyclase, underscoring the interplay between SLC9C1 and cAMP production via sAC." (PMID 41091759, 2025). "Knockout (KO) of Tmem217 in mice resulted in sperm motility defects and male infertility, phenocopying Slc9c1 KO mice." (PMID 41091759, 2025). "In addition to mice, clinical studies link pathogenic variants in SLC9C1 or ADCY10 to asthenozoospermia and male infertility in humans." (PMID 41091759, 2025). "Hence, SLC9C1 is a potential target for the treatment of male infertility, as well as for non-hormonal on-demand male contraceptives, which is analogous to a recent strategy proposed for sAC51." (PMID 37880361, 2023).
asthenozoospermia (2 papers, 2022 to 2025). "Indeed, nearly all pathogenic gene variants that have been described to contribute to asthenozoospermia and male infertility in humans (CASTSPER, SLC26A3, SLC26A8, SLC9C1, VDAC, SLO3) were supported by studies using KO mouse models that show a similar phenotype and pathology." (PMID 35409285, 2022).
cancer (5 papers, 2013 to 2024). A tumor composed of atypical neoplastic, often pleomorphic cells that invade other tissues. "Notably, SLC9C1 mutations were predicted to have low functional impact, thus likely represent passenger mutations, yet SLC9C1 was the most abundantly mutated ABT-SLC pan-cancer and in UCEC." (PMID 37999800, 2024). "Genes such as SLC9C1 have been use to downregulate pH regulation capacity on cancer cells." (PMID 31664702, 2020). "At first, we used the data from TCGA to analyze the mRNA expression of 10 subtypes of NHE family in COAD relative to the adjacent cancer, as well as the clinicopathological related effects (since SLC9B1, SLC9C1, and C2 are only expressed in male testis, they are not within the scope of this study)." (PMID 34759967, 2021).
SLC9C1 also shares sentences with these, for which no sentence is quoted: schizophrenia (2 papers); glioma (1); heart failure (1); Hypertension (1); liver cancer (1); lung carcinoma (1); male fertility (1); Sepsis (1); Shock (1); tumour (1).